CTNNB1 (catenin beta 1)
Diseases named in the same sentence as CTNNB1 in open-access papers (continued):
Sharing a sentence is not in itself a finding about the gene and the disease.
Intellectual disability (26 papers, 2015 to 2025). "Mutations in CTNNB1 are linked to a specific neurodevelopmental syndrome that includes intellectual disability and features of autism." (PMID 41304474, 2025). "Haploinsufficiency of the gene CTNNB1 that encodes β-catenin causes intellectual disability and NDDs, where β-catenin is critical for neural specification and synaptic development." (PMID 40377402, 2025). "CTNNB1 is important in the development and maturation of the brain, and de novo mutations in the gene can cause intellectual disability." (PMID 36833409, 2023). "Most patients with loss-of-function mutations in CTNNB1 showed varying degrees of intellectual disability." (PMID 35935366, 2022). "De novo mutations of the CTNNB1 gene have been associated with neurodevelopmental disorders, with cases of intellectual disability and speech delay." (PMID 36293418, 2022). "As with other Canonical/Wnt pathway disease-associated genes, CTNNB1 mutations result in a range of extra-ocular phenotypes including intellectual disability, developmental and neurological delay." (PMID 35246174, 2022). "Our previous results also provided insight into the relationship between a novel splicing mutation (c.734+1G>A) in CTNNB1 and a 27-year-old Chinese pregnant woman with a severe intellectual disability and FEVR." (PMID 32420371, 2020). "The loss-of-function mutation of the CTNNB1 gene recently has been confirmed as a cause of intellectual disability." (PMID 30929091, 2019). "Diseases associated with CTNNB1, include hairy tumors and intellectual disability, both being 19 autosomal dominant." (PMID 32038705, 2019). "Here, we reported a 27-year-old Chinese pregnant woman with a severe intellectual disability and serious visual defects who was detected with a novel splice mutation (c.734+1G>A) in CTNNB1 gene by whole-exome sequencing and confirmed by Sanger sequencing." (PMID 30929091, 2019). "Recently, a large-scale sequencing firstly identified CTNNB1 loss-of-function mutations as the cause of intellectual disability (ID)." (PMID 30929091, 2019). "Recently, de novo, heterozygous, loss-of-function mutations of the CTNNB1 gene were found that partially explain intellectual disability in some patients." (PMID 28514307, 2017). "We describe an 11 year old male Polish patient with a de novo nonsense mutation in CTNNB1 who in addition to the major features of CTNNB1-related syndrome including intellectual disability and microcephaly, exhibited hyperekplexia and apraxia of upward gaze." (PMID 26968164, 2016). "Mutations of CTNNB1 (β-catenin) have recently been described in patients with a wide range of neurodevelopmental disorders (intellectual disability, microcephaly and other syndromic features)." (PMID 26968164, 2016). "CTNNB1 syndrome is an autosomal-dominant neurodevelopmental disorder featuring developmental delay; intellectual disability; behavioral disturbances; movement disorders; visual defects; and subtle facial features caused by de novo loss-of-function variants in the CTNNB1 gene." (PMID 37895192, 2023). "De novo loss-of-function mutations in the CTNNB1 gene were first discovered in 2012 after diagnostic exome sequencing of individuals with severe intellectual disability, and since then the term CTNNB1 Syndrome has become the generic term for all disorders associated with CTNNB1 haploinsufficiency." (PMID 36293418, 2022). "CTNNB1 gene mutation was firstly reported related to intellectual disability in 2012, to explore the clinical phenotype and genotype characteristics of CTNNB1 mutation, we collected and analyzed the clinical data of a child with a neurodevelopmental disorder caused by a mutation of CTNNB1." (PMID 33425807, 2020). "Therefore, mutations in the CTNNB1 gene could lead to altered transcriptional activity and impaired synaptic plasticity that may result in brain malformation, intellectual disability, and neuronal loss." (PMID 29020091, 2017).
Intellectual disability (continued). "Relatedly, CTNNB1 is involved in multiple NDDs such as intellectual disability, schizophrenia, and ASD, providing further genetic evidence linking Wnt-related components across NDDs." (PMID 40377402, 2025). "Recently, CTNNB1 has also been found involved in neurodevelopmental disorders (NDDs), such as intellectual disability, autism, and schizophrenia." (PMID 37009120, 2023). "Heterozygous germline variants in CTNNB1 have previously been reported as a cause of FEVR, developmental delay and intellectual disability." (PMID 35246174, 2022). "Although most patients share key phenotypes such as global developmental delay and intellectual disability, patients with CTNNB1-related neurodevelopmental disorder show a broad spectrum of clinical features." (PMID 35935366, 2022). "Conversely, de novo loss-of-function mutations in the CTNNB1 gene in ASD probands relates with microcephaly and severe intellectual disability." (PMID 34858139, 2021). "Similarly, mutations in CTNNB1 (encoding β-catenin) are well established in neurodevelopmental disorders such as NEDSDV, which presents with intellectual disability, developmental delay, spastic diplegia, visual defects and autistic characteristics." (PMID 40766181, 2025). "Therefore, although every patient had apparent developmental delay or intellectual disability, seizure or structural brain abnormality would be an uncommon phenotype of CTNNB1-related neurodevelopmental disorder or NEDSDV." (PMID 35935366, 2022). "As already linked with NEDSDV (MIM# 615075) and exudative vitreoretinopathy 7 (MIM# 617572), clinical features such as developmental delay, intellectual disability, spastic diplegia, and ocular problems have been well established in CTNNB1-related neurodevelopmental disorder." (PMID 35935366, 2022).
Wilms tumor (26 papers, 2006 to 2025). An embryonal neoplasm characterized by the presence of epithelial, mesenchymal, and blastema components. "Apart from the IGF2 gene, mutations in the WTX and CTNNB1 genes are also known to be implicated in the pathogenesis of Wilms tumors." (PMID 39272909, 2024). "At least 50% of the Wilms’ tumors with affected WT1 gene display acquired somatic mutations in CTNNB1 gene (Catenin Beta 1 gene), which is located on chromosome 3 (3p22.1)." (PMID 37176098, 2023). "We have shown previously that WT1 mutant Wilms tumors display great heterogeneity of second CTNNB1 mutations in vivo." (PMID 33379206, 2020). "TMEM158 is overexpressed in Wilms tumors (also known as nephroblastoma) with somatic mutations in catenin beta-1 gene suggesting a relationship between the Ras and Wnt signaling pathways." (PMID 30574087, 2018). "Most cell lines that we have established from WT1 mutant Wilms tumors have additional CTNNB1 mutations and the WT1 mutation is either homozygous due to a mitotic recombination event or the cells have a deletion on one allele and a mutation in the other allele." (PMID 27213811, 2016). "Genetic analyses of cells derived from the Wilms tumor (Wilms10) showed the same WT1/11p13 alteration but a different mutation in CTNNB1 as compared to the bulk tumor DNA." (PMID 27213811, 2016). "A highly significant correlation has been found between WT1 mutation and CTNNB1 mutation in Wilms' tumours." (PMID 16909133, 2006). "Notably, CTNNB1 is one of the most frequently mutated genes in Wilms tumors, and up to 50% of Wilms tumors exhibit nuclear accumulation of β-catenin indicative of constitutive activation of the β-catenin pathway." (PMID 39009564, 2024). "In all Wilms tumor cell cultures with a CTNNB1 mutation serine 45 is affected." (PMID 33379206, 2020). "Similarly, activating mutations of CTNNB1 in Wilms tumours highlighted the importance of WNT pathway activation in renal development and in multiple tumour types." (PMID 29912901, 2018). "These genetic alterations (e.g., mutations in CTNNB1 and WTX) or loss of heterozygosity on specific chromosomes (1p, 1q, 11p15, and 16q) have also been linked to nephroblastoma development, highlighting their usefulness in prognostic assessments." (PMID 40142302, 2025). "Some of the most common genetic alterations of pediatric Wilms tumor include IGF2 overexpression, WT1, and CTNNB1 mutations." (PMID 39234402, 2024). "Both CTNNB1 and WT1 mutations have been previously implicated with Wilms’ tumor genesis, and both clone types were present in every profiled region." (PMID 32843649, 2020). "By microdissection of tumor material and ILNR lesions it has been observed that various different CTNNB1 mutations occur in WT1 mutant cells, an example of genetic heterogeneity in Wilms tumor (unpublished observation Uschkereit and BR-P)." (PMID 27213811, 2016). "Here we describe a stromal type Wilms tumor with a homozygous deletion of WT1 nested within a heterozygous 11p13 deletion and a CTNNB1 mutation." (PMID 27213811, 2016).
Wilms tumor (continued). "To investigate this, we comprehensively investigated genetic and epigenetic alterations of three loci – WT1 (11p13), WT2 (11p15.5), and CTNNB1 (3p21) — in 35 sporadic Wilms' tumours." (PMID 16909133, 2006). "To answer both questions, we performed genetic and epigenetic analyses of these loci, together with an additional gene, CTNNB1, in 35 sporadic Wilms' tumours." (PMID 16909133, 2006). "This discovery could elucidate the link between Wilms’ tumour and MNAC as it is already known that CTNNB1 is the most commonly mutated gene in Wilms’ tumour." (PMID 39797200, 2024). "For a long time, the only genes known to be mutated or deregulated in Wilms tumors were WT1, IGF2, and genes linked to canonical WNT signaling (CTNNB1, WTX/AMER1), but recent large-scale sequencing projects have greatly extended the number of genes linked to Wilms tumorigenesis." (PMID 33672414, 2021). "Moreover, mutations in typical Wilms tumour genes were identified, such as WT1, DIS3L2, WTX, CTNNB1 and the miRNA-processing genes DROSHA, DGCR8 and DICER1." (PMID 32161258, 2020). "This subtype of Wilms tumor often carries WT1 mutations and most also harbor CTNNB1 mutations." (PMID 33379206, 2020). "In these Wilms tumors three “hits” occurred; the first is a germ line WT1 mutation, the second is the loss of heterozygosity (LOH) in 11p, resulting in loss of the WT1 wild type allele and the third is a CTNNB1 mutation." (PMID 27213811, 2016). "On the other hand, although WT1 mutation is not frequent, WT1 mutation and CTNNB1 (β-catenin) mutation at 3p21 are significantly correlated with Wilms' tumours." (PMID 16909133, 2006). "Serine 45 is one of the four residues involved in controlling the stability of β-catenin—the protein encoded by CTNNB1—but the reason serine 45 is preferentially hit in Wilms tumor and not the other three residues that are mutated in many other cancer types is not known." (PMID 33672414, 2021). "Both APC and CTNNB1 are classic oncogenes, while AMER1 (also known as the Wilms tumor gene on the X chromosome, WTX) is a tumor suppressor gene." (PMID 31781186, 2019). "Cell culture experiments were performed from primary Wilms tumors and genetic alterations in WT1 and CTNNB1 analyzed." (PMID 29542868, 2018). "Nephroblastoma generally does not harbour mutations of BRAF but tends toward other genetic alterations, including, but not limited to WT1 and CTNNB1 mutations." (PMID 40177273, 2025). "The causes for Wilms tumors are not precisely known, but gene alterations of WT1, CTNNB1, and WTX have been found in about 30%." (PMID 34073340, 2021). "Taken together, in this WT1 mutant Wilms tumor no other clear pathogenic mutations except for WT1 and CTNNB1 are found." (PMID 33379206, 2020). "Microdissection of ILNRs in WT1 mutant Wilms tumors revealed that these carry biallelic WT1 mutations but no CTNNB1 mutations, whereas the associated tumor cells had CTNNB1 mutations." (PMID 27213811, 2016). "This frequency is comparable to that of known Wilms tumor suppressors WT1 and CTNNB1." (PMID 21080955, 2010).
endometrioid carcinoma (24 papers, 2009 to 2025). "Mutations in CTNNB1 are frequently observed in low- and intermediate-grade endometrioid carcinomas, but are less common in PDEECs." (PMID 40072110, 2025). "In PDEECs, particularly high-grade endometrioid adenocarcinomas, CTNNB1 mutations contribute to more aggressive cancer phenotypes and poorer clinical outcomes." (PMID 40072110, 2025). "In particular, high-grade endometrioid carcinomas with CTNNB1 mutations display aggressive behavior, with poorer prognosis and an increased likelihood of recurrence compared to those without the mutation." (PMID 40072110, 2025). "The results showed that there are 130 mutations of CTNNB1 in 399 cases of endometrioid adenocarcinoma, including 2 cases with mutation of D32A." (PMID 37328769, 2023). "For instance, while low-grade endometrioid carcinomas with CTNNB1 mutations may exhibit relatively indolent behavior, high-grade tumors tend to have a more aggressive clinical course." (PMID 40072110, 2025). "However, the heterogeneous clinical course of endometrioid carcinoma is still an obstacle to individualized treatment.Mutations in the CTNNB1 exon 3 hotspot were suggested to be drivers of a more aggressive subtype of low-grade, early-stage endometrioid endometrial carcinoma." (PMID 37328769, 2023). "Endometrioid carcinomas, which originate from the same tissue as OCCC, have been shown to frequently harbor mutations in genes such as CTNNB1 (42% of samples), KMT2D (31%), KMT2B (19%), and PIK3R1 (19%)." (PMID 33153119, 2020). "Other mutations, such as those of the CTNNB1 and PTEN genes, have also been reported in endometrioid carcinoma related to endometriosis." (PMID 33308243, 2020). "In endometrioid carcinoma, PTEN mutations are associated with other mutations found in KRAS proto-oncogene, Catenin Beta 1 (CTNNB1), and PIK3CA genes and microsatellite instability, which results in short DNA sequence alterations and its ultimate replication." (PMID 34322276, 2019). "PIK3CA variant was identified with VAF 82.8% in NEC, 75.2% in endometrioid carcinoma, 37.2% in ovarian endometriosis, and 77.2% in uterine EAH, while CTNNB1 variant was identified with VAF 76.9% in NEC, 64.6% in endometrioid carcinoma, 16.3% in ovarian endometriosis, and 68.7% in uterine EAH." (PMID 34342838, 2022). "The mutations of PIK3CA and CTNNB1 genes, as well as the alteration of the SWI/SNF complex, that was documented in our case by the loss of ARID1A expression, are among the most common and earliest genetic abnormalities detected in endometrioid carcinoma." (PMID 34342838, 2022). "employed a 4-gene panel (CTNNB1, PTEN, KRAS, and PIK3CA) to analyze paired plasma and tumor tissues from 48 cases of endometrioid carcinoma." (PMID 40860812, 2025).